HNRNPCL3 (heterogeneous nuclear ribonucleoprotein C like 3)
Tractability: PROTAC: ubiquitination databases record sites on it.
Gene: Protein-coding gene on chromosome 1 (13,060,769 to 13,062,878, forward strand). Ensembl gene ENSG00000277058.
Subcellular location: Nucleus
Subcellular location (Human Protein Atlas): Nucleoplasm
Gene Ontology:
Molecular function: RNA binding; nucleic acid binding
Cellular component: nucleus
Genetic constraint (gnomAD): Loss-of-function variants: 0 observed, 2.61 expected, observed/expected ratio (o/e) 0, 90% interval 0 to 1.11. That is too few expected variants to judge how well the gene tolerates losing a copy. Missense variants: 3 observed, 30.7 expected, observed/expected ratio (o/e) 0.0977, 90% interval 0.044 to 0.25. Synonymous variants: 1 observed, 11.37 expected, observed/expected ratio (o/e) 0.0879, 90% interval 0.03 to 0.42.
Homologues: Orthologues: rabbit HNRNPC (88% identical), mouse Hnrnpc (87% identical), rat LOC100911576 (87% identical), tropical clawed frog hnrnpc (73% identical). Paralogues in human: HNRNPCL4 (100% identical), HNRNPCL1 (94% identical), HNRNPCL2 (92% identical), HNRNPC (88% identical), RALYL (44% identical), RALY (43% identical).